ENSG00000287279 (novel transcript)
Gene: Long non-coding RNA gene on chromosome 6 (28,634,783 to 28,653,506, forward strand). Ensembl gene ENSG00000287279.
Gene Ontology:
Molecular function: triplet codon-amino acid adaptor activity
Biological process: translation